DCLRE1A (DNA cross-link repair 1A)
Description:
May be required for DNA interstrand cross-link repair. Also required for checkpoint mediated cell cycle arrest in early prophase in response to mitotic spindle poisons. Possesses beta-lactamase activity, catalyzing the hydrolysis of penicillin G and nitrocefin. Exhibits no activity towards other beta-lactam antibiotic classes including cephalosporins (cefotaxime) and carbapenems (imipenem).
Synonyms: hSNM1; KIAA0086; SNM1; SNM1A; PSO2
Tractability: Small molecule: a structure with a bound ligand is known. PROTAC: UniProt records ubiquitination sites on it; ubiquitination databases record sites on it.
Target class: Other nuclear protein
Gene: Protein-coding gene on chromosome 10 (113,834,725 to 113,854,383, reverse strand). Ensembl gene ENSG00000198924.
Subcellular location: Nucleus
Subcellular location (Human Protein Atlas): Nucleoplasm; Nucleoli fibrillar center
Pathways (Reactome):
DNA Repair: Fanconi Anemia Pathway
Gene Ontology:
Molecular function: 5'-3' DNA exonuclease activity; beta-lactamase activity; damaged DNA binding; DNA binding
Biological process: double-strand break repair via nonhomologous end joining; interstrand cross-link repair; DNA repair
Cellular component: nucleoplasm; nucleus
Genetic constraint (gnomAD): Loss-of-function variants: 65 observed, 93.33 expected, observed/expected ratio (o/e) 0.7, 90% interval 0.57 to 0.86. The upper end of that interval is the gene's LOEUF score, 0.86, which puts it in group 3 of 6, group 1 being the genes least tolerant of losing a copy. Missense variants: 1,142 observed, 1,276.2 expected, observed/expected ratio (o/e) 0.89, 90% interval 0.85 to 0.94. Synonymous variants: 416 observed, 455.63 expected, observed/expected ratio (o/e) 0.91, 90% interval 0.84 to 0.99.
Homologues: Orthologues: chimpanzee DCLRE1A (99% identical), macaque DCLRE1A (93% identical), dog DCLRE1A (74% identical), pig DCLRE1A (73% identical), rabbit DCLRE1A (72% identical), mouse Dclre1a (63% identical), rat Dclre1a (62% identical), guinea pig DCLRE1A (56% identical), tropical clawed frog dclre1a (36% identical), zebrafish dclre1a (34% identical), Drosophila melanogaster Snm1 (18% identical). Paralogues in human: DCLRE1B (11% identical), DCLRE1C (10% identical).
Diseases named in the same sentence as DCLRE1A in open-access papers:
DCLRE1A is named in the same sentence as 10 diseases in open-access papers, as found by Europe PMC text mining. Sharing a sentence is not in itself a finding about the gene and the disease. The quoted sentences say what the papers report.
Fanconi anemia (6 papers, 2013 to 2021). Fanconi anemia (FA) is a hereditary DNA repair disorder characterized by progressive pancytopenia with bone marrow failure, variable congenital malformations and predisposition to develop hematological or solid tumors. "Protein interaction analysis indicates that this “genic signature” (Dclre1a, Rev1, Xpa, Pms2, Brca2, Parp2, Smc3, Nbn, Bax) is mainly involved in the Fanconi anemia pathway and homologous recombination repair." (PMID 34573315, 2021). "The Fanconi anemia pathway genes FANCB, POLN, DCLRE1A, UBA52, and FANCF genes were significantly (p < 0.01, T-test) downregulated after radiation only in FANCA-deficient HIO lines." (PMID 32085439, 2020).
lung carcinoma (2 papers, 2009 to 2016). "In addition, a significant association between DCLRE1A and the development of lung cancer has been observed." (PMID 19919702, 2009).
neuroblastoma (1 paper, 2018). Neuroblastoma (NB) is the most common solid, extracranial childhood tumor. "The mutation of the double strand break repair gene DCLRE1A is of particular interest as impairment of the non-homologous end joining process is believed to be the cause of the characteristic copy number changes in neuroblastoma." (PMID 29492199, 2018).
ovarian carcinoma (1 paper, 2016). A malignant neoplasm originating from the surface ovarian epithelium. "The network based approach identified two 7-gene functional interaction modules (31: DCLRE1A, EXO1, KIAA0101, KIN, PCNA, POLD3, POLD2; 35: DKK3, FABP3, IRF1, AIM2, GBP1, GBP2, IRF2) that are associated with prognosis of ovarian cancer patients." (PMID 27806724, 2016).
tumours (7 papers, 2007 to 2024). "Similar to DCLRE1A, Exo1 is also shown to be higher expressed in tumor tissues than that in the normal tissues." (PMID 27806724, 2016).
infection (1 paper, 2020). The state of being infected such as from the introduction of a foreign agent such as serum, vaccine, antigenic substance or organism. "Response to stress (MT1X), repair process (DCLRE1A), and T cell activation-related genes (B2M) were the most important upstream regulators during the decline phase of the gt3 infection." (PMID 32877413, 2020).
DCLRE1A also shares sentences with these, for which no sentence is quoted: cancer (7 papers); bacterial infection (1); colorectal cancer (1); prostate carcinoma (1).